INS (insulin)
Diseases named in the same sentence as INS in open-access papers (continued):
Sharing a sentence is not in itself a finding about the gene and the disease.
type 2 diabetes (continued). "It is possible that RGCs become unresponsive to insulin in patients with type 2 diabetes, and, although it remains to be tested, this can potentially increase the susceptibility of RGCs to glaucomatous damage." (PMID 39110798, 2024). "Essentially, the study suggests that an FMD can reprogram pancreatic cells to renew insulin production in type 1 diabetes patients’ islets and mitigate symptoms of both type 1 and type 2 diabetes in mice." (PMID 38321992, 2024). "Type 2 diabetes was present in 33% (n = 103) of patients, which was treated with the following strategies: sulfonylureas 24%, metformin 49%, insulin 16%, thiazolidinediones 3%." (PMID 38623877, 2024). "Some ergot derivatives, like bromocriptine, are used in managing type II diabetes by impacting glucose metabolism and insulin sensitivity." (PMID 39849925, 2024). "CGM can capture glucose variations, guide insulin therapy optimisation and improve glucose levels and hypoglycaemia detection in individuals with insulin-treated type 2 diabetes receiving dialysis." (PMID 38951212, 2024). "Taken together, our exploratory results demonstrate that both RYGB and SG have the potential to partially restore beta-cell function in patients with insulin-treated type 2 diabetes and considerably impaired beta-cell function three weeks after surgery." (PMID 38589596, 2024). "Noninvasive, longitudinal, and intravital microimaging reveals the in vivo dynamic profiles of β-cell [Ca2+]i, function and mass as well as insulin resistance in intracameral islet grafts during the development of type 2 diabetes." (PMID 38206586, 2024). "Type 2 diabetes mellitus (T2DM) is a prevalent metabolic disorder characterized by elevated blood glucose levels resulting from impaired insulin secretion, action, or both." (PMID 38553719, 2024). "In contrast, type 2 diabetes is distinguished by an increased insulin insufficiency and a comparable shortfall in insulin activation." (PMID 38357071, 2024). "Genome-wide association studies have revealed the localization of the human COBLL1 gene in genomic regions associated with metabolism, including high-density cholesterol, triglyceride metabolism, insulin levels, type 2 diabetes, and other metabolic disorders." (PMID 38699158, 2024). "In humans with type 2 diabetes, short-term cold exposure activates brown/beige fat and improves insulin sensitivity." (PMID 39062047, 2024). "Managing type 2 diabetes often involves lifestyle changes, diet, physical activity, and oral medications or insulin in some cases." (PMID 38673817, 2024). "Effective glucose monitoring is an important aspect of the management of those with type 2 diabetes on insulin therapy." (PMID 38932793, 2024). "In adults with established type 2 diabetes, lower IGFBP-1 remains associated with cardiovascular risk factors including fasting insulin, LDL cholesterol and BMI." (PMID 39595651, 2024). "Accurate identification of the efficacy of different insulins in not only maintaining glycaemic control but also limiting hypoglycaemia is of fundamental importance to people with type 1 diabetes or insulin-treated type 2 diabetes." (PMID 38795153, 2024). "SRSF6 silencing modulates splicing of genes involved in beta cell apoptosis, JNK signalling, insulin secretion, and type 2 diabetes." (PMID 38081640, 2024). "Icodec and basal insulin Fc (BIF, also known as insulin efsitora alfa or LY3209590) are the two most advanced once-weekly basal insulins for the treatment of patients with type 1 or type 2 diabetes." (PMID 39629047, 2024). "Type 2 diabetes mellitus (T2DM) is due to a progressive insulin secretory defect in the context of IR8." (PMID 37957232, 2023). "It is reasonable to start insulin therapy for patients with type 2 diabetes who present with severe hyperglycaemia." (PMID 36461758, 2023).
type 2 diabetes (continued). "The major consequence of IR, type 2 diabetes, arises when people who are insulin-resistant are unable to maintain the level of hyperinsulinemia required to correct the insulin action deficiency." (PMID 37443718, 2023). "On the other hand, resveratrol seems to raise blood insulin levels in rodent models of type II diabetes with reduced-cell mass and hypoinsulinemia, as demonstrated in db/db mice." (PMID 37241737, 2023). "In a recent online survey, 39% of patients with insulin-treated type 2 diabetes reported discussing severe hypoglycaemia at every clinic visit." (PMID 38076413, 2023). "In contrast, in people with type 2 diabetes, abnormalities in insulin and glucagon secretion rates persisted during hyperglycemia — in the latter case, to the point that hyperglycemia and hyperinsulinemia are insufficient to suppress EGP." (PMID 37751301, 2023). "The thiazolidinedione class of PPARγ agonists, including rosiglitazone and pioglitazone, are used in the treatment of type 2 diabetes by improving insulin sensitivity." (PMID 36928191, 2023). "Insulin amyloid fibrils were found in patients with type II diabetes mellitus after the repeated or even single subcutaneous injection of insulin." (PMID 37629113, 2023). "Type 1 and type 2 diabetes arise from a failure in insulin production or from resistance to insulin action, respectively." (PMID 37049607, 2023). "Due to reductions in insulin sensitivity and secretion, statin therapy elevated the incidence of type 2 diabetes by 46%." (PMID 37465091, 2023). "Other CpGs in the region of DHCR24 (cg17901584 and cg27168858) have been associated with HDL-cholesterol (HDL-C), triglycerides, fasting insulin, BMI, HbA1c, incident type 2 diabetes, statin use, waist circumference and LDL-C." (PMID 37202507, 2023). "Such abnormality in the insulin response to glucose has previously been suggested to precede the development of type 2 diabetes." (PMID 36674879, 2023). "Type 2 diabetes (T2D), the most common, is characterized by insulin resistance and low or null production of insulin." (PMID 37538927, 2023). "We discovered a significant increase in the insulin resistance indices in elderly patients with type 2 diabetes during the COVID-19 infection, which was reduced after complete remission." (PMID 36846644, 2023). "COVID-19 infection can impact type 2 diabetes through alterations in adipose tissue mass, cytokines levels, and insulin sensitivity." (PMID 38292772, 2023). "In type 1 diabetes, damaged pancreatic β cells stop producing insulin; in type 2 diabetes, genetic factors related to inadequate insulin secretion are the main cause." (PMID 36768946, 2023). "The SUVmean was lower in individuals with type 2 diabetes who received glucose-lowering drugs (oral glucose-lowering drugs and/or exogenous insulin) compared with those who were prescribed dietary and lifestyle changes (4.5±2.0 vs 6.1±2.5, p=0.15)." (PMID 37935826, 2023). "Leptin interferes with insulin signaling, and in type II diabetes, plasma leptin levels correlate with the degree of IR, a relationship independent of BMI and body fat mass." (PMID 36922570, 2023). "Type 2 diabetes (T2D) is characterized by a chronic elevation of blood sugar levels due to insulin resistance and impaired insulin secretion, resulting in disturbances in the regulation of carbohydrate, lipid, and protein metabolism." (PMID 38069193, 2023). "Type 2 diabetes is characterised by chronic raised blood glucose levels due to a lack of insulin produced by the pancreas or ineffective use of the insulin produced." (PMID 36839218, 2023). "It is also associated with a reduction in postprandial peak glucose and insulin, which is a point of interest for people with type 2 diabetes or subjects with glucose intolerance." (PMID 37571355, 2023).
type 2 diabetes (continued). "In type 2 diabetes, the incretin effect (greater insulin secretory response after oral glucose than with ‘isoglycaemic’ i.v. glucose, i.e. with an identical glycaemic stimulus) is markedly reduced or absent." (PMID 37430117, 2023). "The majority of diabetic patients suffer from type 2 diabetes (T2DM) where the body cannot effectively make use of the insulin it produces." (PMID 37259043, 2023). "Type II diabetes is treated with insulin while Type II diabetes can be treated with drugs that lower glucose independently of insulin." (PMID 37504117, 2023). "Univariable MR analyses of fasting insulin (FI) and glycated hemoglobin (HbA1c) as outcome followed by multivariable MR adjusted for elevated fasting glucose (FG), type 2 diabetes (T2D) and increased hemoglobin (Hb)." (PMID 37008938, 2023). "The DIME intervention was acceptable and feasible to deliver to participants with type 2 diabetes starting insulin in South London, UK." (PMID 37237318, 2023). "Type 2 diabetes (T2D) is a chronic condition that occurs in insulin-resistant people with reduced glucose uptake." (PMID 37049602, 2023). "All patients with type 1 and some patients with type 2 diabetes take insulin as a part of their regimen for glycemic control." (PMID 37120562, 2023). "For example, chronic BNP infusion has been shown to improve glucose homeostasis, insulin sensitivity, and increase lipid oxidative capacity in the skeletal muscle tissue of obese and Type 2 diabetic mice." (PMID 37917630, 2023). "The evidence on the effects of metformin and insulin in type 2 diabetes patients on quality of life, patient satisfaction, and cardiovascular outcomes is unclear." (PMID 36923108, 2023). "The four traditional Chinese exercise therapies can improve blood glucose levels, blood lipid levels and insulin-related indicators of type 2 diabetes to varying degrees." (PMID 38093392, 2023). "The inhibition of alpha-glucosidase is critical for the effective management of type-2 diabetes, which is distinguished by hyperglycemia, resistance to insulin, and insufficient insulin secretion." (PMID 38002116, 2023). "Conversely, when insulin levels are low (during fasting or in the late stages of type 2 diabetes), elevated IGFBP-1 levels inhibit IGF-I mediated effects." (PMID 36901984, 2023). "Previous studies have associated 11β-HSD-2 regulation with blood pressure, insulin sensitivity, and type 2 diabetes." (PMID 36810558, 2023). "For individuals with type 2 diabetes, impaired insulin secretion during the post-meal digestion process leads to postprandial hyperglycemia, which in turn triggers metabolic abnormalities in the liver or pancreas." (PMID 38068845, 2023). "We studied the effects of conditioning on blood glucose, insulin, and C-peptide levels in patients with diabetes type 2 and healthy controls." (PMID 37234022, 2023). "Insulin resistance and initial hyperglycemia are the primary pathophysiology characteristics of type 2 diabetes, followed by a gradual decline in the ability of pancreatic β cells to produce insulin." (PMID 37964315, 2023). "Type 2 diabetes (T2D), which accounts for more than 90% of diabetic cases, is characterized by a pancreas that cannot produce sufficient insulin." (PMID 37003602, 2023). "In type 2 diabetes, hyperglycemia is the result, initially, of the inability of the body’s cells to respond fully to insulin, a condition termed insulin resistance." (PMID 38155289, 2023). "Metformin and insulin have been shown to improve β-cell function in adults with new-onset type 2 diabetes." (PMID 38234946, 2023). "In type II diabetes, insulin binds to the insulin receptor, but there is a failure to activate the insulin signalling cascade, resulting in a loss of glucose transport into cells and ultimately high blood glucose levels." (PMID 37621079, 2023). "From being used exclusively in type 1 diabetes, there is an increase in utilization of insulin pumps for the treatment of type 2 diabetes." (PMID 37120562, 2023).
type 2 diabetes (continued). "Can a voice-based conversational artificial intelligence (AI) application help patients with type 2 diabetes titrate basal insulin at home to achieve rapid glycemic control?" (PMID 38039007, 2023). "Type 2 diabetes (T2DM) is a chronic metabolic disease characterized by elevated blood glucose levels due to inadequate insulin secretion." (PMID 37223029, 2023). "In early type 2 diabetes, “induction” with short-term insulin therapy followed by “maintenance” with metformin can stabilize beta-cell function." (PMID 37500612, 2023). "Two forms of hyperinsulinemia with different mechanisms were identified through PEG precipitation in type 2 diabetic patients who were receiving insulin or insulin analog treatments." (PMID 37324170, 2023). "The latest research evaluating IF in people with type 2 diabetes on insulin therapy revealed significantly reduced HbA1c, body weight and insulin dose in comparison to the standard of care." (PMID 36979064, 2023). "Type 2 diabetes mellitus (T2DM), which is characterized by hyperglycemia resulting from progressive loss of adequate insulin production in the setting of insulin resistance, has been identified as a serious global health threat by WHO." (PMID 37522116, 2023). "Type 2 diabetes mellitus (T2DM) is a complex metabolic disease linked to beta-cell dysfunction, insulin resistance, and impaired insulin secretion." (PMID 38031191, 2023). "Firstly, insulin, a hormone recognized for its regulatory function in bone anabolism, is believed to play a pivotal role in the pathogenesis of type 2 diabetes." (PMID 37782659, 2023). "Adults with type 2 diabetes treated with insulin who had a GLP-1 RA added to their regimen were evaluated retrospectively." (PMID 37589043, 2023). "In particular, 37.7% of patients with type 2 diabetes were treated with metformin, 37.3% with insulin therapy, 16.4% with sulfonylureas, and 11.4% with glinides." (PMID 36964858, 2023). "The only comparable and recent randomized clinical trial studied the application of rtCGM-guided insulin administration in 185 general medicine and surgery patients with type 1 and type 2 diabetes." (PMID 37736430, 2023). "ASNA-1 (TRC40) and ENPL-1 (GRP94) are conserved insulin secretion regulators in Caenorhabditis elegans (and mammals), and mouse Grp94 mutants display type 2 diabetes." (PMID 36939052, 2023). "In conclusion, routinely measuring FINS levels was necessary in subjects with type 2 diabetes who were receiving insulin or insulin analogs treatment." (PMID 37324170, 2023). "Arginine supplementation improves insulin sensitivity in healthy people, obese people, type 2 diabetes and coronary artery disease." (PMID 37600949, 2023). "In patients with type 2 diabetes treated with insulin therapy in whom hypoglycemia predominates, a rtCGM with predictive alerts and alarms should be used." (PMID 37676398, 2023). "Insulin injection is the most effective tool for glycemic control in patients with type 1 diabetes (T1D) and type 2 diabetes (T2D)." (PMID 36658284, 2023). "Insulin therapy for Type 2 diabetes enhanced skeletal muscle index (SMI) and protected against Sarcopenia, a loss of skeletal muscle mass and strength that occurs with age and is a primary cause of disability and mobility limits." (PMID 36942499, 2023). "Most patient with type 2 diabetes (88%) were treated with anti-diabetic drugs including insulin (23%)." (PMID 37430240, 2023). "Oral administration of P. ostreatus and P. cystidiosus at a dose of 50 mg/kg/body weight has been shown to increase serum insulin levels and decrease postprandial serum glucose levels in patients with type 2 diabetes." (PMID 36985818, 2023). "Sulfonylureas: Second-line agents like glipizide and glimepiride fall under the category of sulfonylureas, which function by stimulating insulin secretion and are commonly used in the treatment of type 2 diabetes." (PMID 37965396, 2023).
type 2 diabetes (continued). "One previous systematic review assessed the effects of adding metformin to insulin in people with type 2 diabetes." (PMID 36923108, 2023). "In individuals with type 2 diabetes, exercise improves glucose tolerance and insulin sensitivity, which in turn decreases the development of CKD." (PMID 38455919, 2023). "Several reports associated both species with enhanced intestinal integrity, reduced levels of inflammation and improved insulin sensitivity in type 2 diabetes when mice were orally treated with living bacterial strains." (PMID 38147032, 2023). "It was demonstrated that it presents anticancer activity towards the non-small cancer lung cell (NSCLC) lines, and was able to induce insulin release from rat- and human-derived beta cells with potential use for type 2 diabetes treatment." (PMID 36982501, 2023). "We also aim touse the UKPDS model to assess the data of people with type 2 diabetes who areprescribed insulin and determine an appropriate model to analyze the data of thosewith type 1 diabetes." (PMID 34986658, 2023). "GLP-1 RA is preferred over insulin when stronger glucose lowering is needed in patients with type 2 diabetes." (PMID 37808605, 2023). "The insulin-antagonistic hormone glucagon has been suggested as a key player in the development of type 2 diabetes, along with other hormonal and neural systems." (PMID 36752854, 2023). "On the other hand, type 2 diabetes is often due to relative overnutrition, with normal endocrine function and variable insulin levels." (PMID 37313244, 2023). "This study aims to investigate the association between dietary insulin index (DII) and load (DIL) with cardiometabolic risk factors and the risk of developing metabolic syndrome (MetS) among patients with type 2 diabetes (T2DM)." (PMID 38049837, 2023). "A multicenter post hoc study investigated the effects of tirzepatide (1, 5, 10, and 15 mg) and dulaglude (1.5 mg) versus placebo on markers of β cell function and insulin sensitivity in 360 subjects with type 2 diabetes." (PMID 37729025, 2023). "The benefits associated with CGM, in terms of improved HbA1c and reduced glycemic variability, are also emerging in studies involving older people with type 2 diabetes using insulin." (PMID 37676398, 2023). "β-cell defects in type 2 diabetes have two components: reduction in the count of β-cells and gradual impairment in its function to boost insulin production in response to blood sugar." (PMID 38094528, 2023). "GLP-1 and GIP hormones play important roles in regulating insulin secretion and management of Type 2 diabetes by augmenting glucose-stimulated insulin secretion via the cAMP signaling pathway." (PMID 37133312, 2023). "The aim of the present study was to investigate the effects of conditioning with intranasal insulin on blood glucose, insulin, C-peptide, hunger, and memory in a group of patients with diabetes type 2 and age- and sex-matched healthy controls." (PMID 37234022, 2023). "In a randomized, crossover trial in adults with type 2 diabetes, fully closed-loop insulin delivery increased time in target glucose range compared with standard insulin therapy, without increasing hypoglycemia." (PMID 36631592, 2023). "Recently, oral insulin administration for managing type 2 diabetes developed as an alternative method to the traditional delivery of insulin through injection." (PMID 36998008, 2023). "Testosterone protects against type 2 diabetes in men, possibly due to improvement in body composition and insulin sensitivity." (PMID 36624450, 2023). "Understanding the effects of POA on insulin sensitivity and lipogenesis has the potential for a profound public health impact in the fight against obesity and type 2 diabetes." (PMID 38313838, 2023). "In conclusion, the progression towards type 2 diabetes is characterised by changes in the expression of ER stress/UPR-related genes, and consequent defects in intra-islet insulin synthesis leading to loss of beta cell identity and dysfunction." (PMID 36280617, 2023).